HMGB1 (high mobility group box 1)
Diseases named in the same sentence as HMGB1 in open-access papers (continued):
Sharing a sentence is not in itself a finding about the gene and the disease.
tumor (continued). "Moreover, HMGB1 is commonly expressed on inflammatory, stressed, and necrotic cells as a Danger Associated Molecular Pattern (DAMP) protein and increases substantially in cancer cells as a tumor-derived danger signal." (PMID 37511951, 2023). "In addition, danger signals, such as high-mobility group box 1 (HMGB1), released from immunogenically dying tumor cells can activate DCs via interactions with pattern-recognition receptors and facilitate antigen presentation by DCs, leading to enhanced antigen-specific T cell responses." (PMID 37553327, 2023). "Such tumour microenvironment remodelling via HMGB1 blockade could work synergistically with current anti-cancer therapies, and our study suggests that a similar effect may be true for HMGB1 in CRC." (PMID 36980751, 2023). "Indeed, blockage of the HMGB1/RAGE axis has been shown to reduce tumor growth and metastasis." (PMID 37627239, 2023). "Therefore, we hypothesized that enhanced cellular uptake of Lf-GL provided more benefit in arresting nuclear-to-cytoplasmic translocated-HMGB1 as an important factor in the disturbance of tumor cell proliferation compared with other treatment groups." (PMID 37210579, 2023). "Moreover, HMGB1 silencing was shown to sensitize tumor cells to chemo-radio therapeutic modalities." (PMID 37098542, 2023). "Factors involved in tumor-mediated NET formation include tumor-derived inflammatory and chemoattractant cytokines (IL-8, IL-6, TNF-α, G-CSF and IL-1β), tumor extracellular vesicles, tumor-activated platelets, tumor-derived HMGB1, KRAS oncogene mutation and hypoxia." (PMID 37511453, 2023). "Indeed, combination therapy increased CRT exposure in tumor cells and the release of HMGB1." (PMID 37705051, 2023). "Therefore, considering the tumor microenvironment in which tumors deteriorate through HMGB1, GL, which has both antitumor and HMGB1 inhibitory effects, could play a pivotal role in GBM treatment." (PMID 37210579, 2023). "Furthermore, in the present study, we focused on extracellular HMGB1 concentrations and investigated the effects of rTM, which may exert anti-tumor effects by decreasing the HMGB1 concentrations." (PMID 35328684, 2022). "TCPP-TER could selectively accumulate in the ER of tumor cells upon NIR irradiation and locally induce ROS production that triggered oxidative stress of ER, which resulted in increased expression of CRT and HMGB1, and then elicited a stronger immune response of tumor suppression." (PMID 35910806, 2022). "Necroptosis cells release cellular contents, such as HMGB1, which recruit immune inflammatory cells to liberate growth factors and prosurvival factors, prosurvival factors and proangiogenic factors to promote tumor invasion and metastasis, as well as resistance to hormonal and chemotherapy." (PMID 36065304, 2022). "In addition, low DNA methylation of HMGB1 was found in most tumours with high HMGB1 expression." (PMID 35765707, 2022). "Thus, the manipulation of tumor-derived HMGB1 might be applicable to improve the clinical outcomes of cancer immunotherapies including ICB and cancer vaccine therapies." (PMID 35150340, 2022). "Therefore, the role of HMGB1 in anti-tumor immunity is complicated, and it is unclear whether HMGB1 has a favorable or unfavorable impact on the host defense against tumors." (PMID 35150340, 2022). "Furthermore, blockade of HMGB1 by using HMGB1-blocking antibodies inhibits tumor growth." (PMID 35408786, 2022). "Autophagosome-derived exosomes obtained from malignant effusions of cancer patients could activate the differentiation of human B cells into IL-10-producing B cells with immunomodulatory activities, with the level positively correlating with HMGB1 expression on tumor cell-released autophagosomes." (PMID 36233088, 2022). "However, active secretion of HMGB1 has been uncovered in tumor cells." (PMID 35927755, 2022).
tumor (continued). "At the same time, HMGB1 can be secreted or released out of the cell as a damage-related model molecule that binds to its receptor to participate in inflammation, cell differentiation, cell migration, angiogenesis and tumor metastasis, drug resistance, and so on." (PMID 35886594, 2022). "Thus, HMGB1 would seem to play a positive role in host defense; on the other hand, it is known that inflammation, including HMGB1-induced inflammation, in the tumor microenvironment contributes to tumor promotion and progression." (PMID 35150340, 2022). "Therefore, as an alarmin, HMGB1 can be actively secreted by various inflammatory cells, passively released by necrotic and apoptotic cells, and selectively released through tumor cell autophagy." (PMID 36275647, 2022). "This could be due to the rather stable presence of plasma HMGB1 during shrinkage of the tumor." (PMID 35336794, 2022). "Thus, manipulation of tumor-derived HMGB1 might be applicable to improve the clinical outcomes of cancer immunotherapies, including immune checkpoint blockades and cancer vaccine therapies." (PMID 35150340, 2022). "Previous study found impaired PINK1 and PRKN expression could promote the degradation of SLC25A37 and SLC25A28 and increase the mitochondrial iron accumulation, which lead to AIM2-mediated HMGB1 release that further induced expression of CD274/PD-L1 in tumor cells." (PMID 36612054, 2022). "In addition, CRT surface exposure and release of HMGB1 and ATP were significantly higher in tumor cells irradiated with 25 mW power of micro-LEDs, resulting in upregulated maturation and phagocytic activity of DCs when those tumor cells were co-cultured with DCs." (PMID 36258234, 2022). "However, both inhibitors could reverse the HMGB1-induced B-cell activation in tumor growth, indicating the importance of in situ ESCC-derived HMGB1–B-cell interactions in the protumor response." (PMID 34617194, 2022). "Thus, manipulation of tumor derived HMGB1 might be applicable to improve the clinical outcome of cancer therapies, including immune checkpoint blockades and cancer vaccine therapies." (PMID 36012593, 2022). "Interestingly, hypoxia and the concomitant presence of HMGB1, are reported to promote M2-macrophage retention in the tumor hypoxic core of the TME, through a RAGE-dependent mechanism, by decreasing both the expression of CCR2 and the migration capacity of M2 macrophages." (PMID 35727208, 2022). "However, the role of the multifunctional HMGB1 in the molecular pathogenesis of different tumours remains unclear." (PMID 35765707, 2022). "Therefore, the algorithms of TIMER, CIBERSORT, CIBERSORT‐ABS, QUANTISEQ, XCELL, MCPCOUNTER and EPIC were used to study the potential relationship between the expression of HMGB1 and the infiltration level of different immune cells in TCGA for different tumour types." (PMID 35765707, 2022). "However, whether HMGB1 release is involved in tumor repopulation at the early and late responses to BNCT should be evaluated in future studies in xenograft models." (PMID 35336794, 2022). "Moreover, HMGB1 and its interaction with the RAGE receptor on tumor cells could also directly regulate tumor cell autophagy and result in HMGB1-mediated tumorigenesis." (PMID 35432318, 2022). "Thus, the levels of CRT and HMGB1 in tumor tissues were examined." (PMID 35541893, 2022). "Furthermore, HMGB1 can enhance tumor migration and invasion abilities through EMT formation." (PMID 36384979, 2022). "However, when used in combination with cytotoxic agents, it may suppress the release of extracellular HMGB1 from necrotic cells, inflammatory cells, and tumor cells, and prevent the metastasis of remaining tumor cells." (PMID 35328684, 2022). "Additionally, we observed that the high expression of HMGB1 was significantly correlated with tumor dysfunction and exclusion (TIDE), and the results illustrate that the high expression of HMGB1 allows tumor cells to evade immune surveillance and promote tumor growth." (PMID 36230798, 2022).
tumor (continued). "However, whether HMGB1 expressed on tumor cells can induce pro- or antitumorigenic B-cell production in ESCC is, however, totally unknown." (PMID 34617194, 2022). "Moreover, a novel fusogenic oncolytic vaccinia virus (FUVAC) displayed fusogenic cytopathic effects resulting in cell-cell fusion, apoptosis, necrosis, and ICD via HMGB1 and ATP release, which increased CD8+ T cell infiltration and decreased tumor-associated immune repressive cells." (PMID 36755812, 2022). "Furthermore, local anaesthetics in high concentration have recently been proven to trigger T lymphocyte-dependent tumour growth reduction through ER stress induction and eliciting other immunostimulatory stress signals including the release of ATP and HMGB1 from cancer cells." (PMID 36612205, 2022). "Thus, HMGB1 plasma level could possibly be used as a biomarker for monitoring the early tumor response to BNCT." (PMID 35336794, 2022). "However, HMGB1 may promote tumor invasion, while metastasis reduces anti-tumor immunity by interacting with the receptor for advanced glycation end products (RAGE) and T-cell immunoglobulin domain and mucin domain 3 (TIM3)." (PMID 36145510, 2022). "According to the recent report on the immunostimulatory activity of HMGB144, we hypothesized that HMGB1 could bind to the concurrently released tumor-derived dsDNA and shuttle them to DCs to activate the cGAS-STING pathway therein after the nanoassembly-induced ICD of tumor cells." (PMID 36167857, 2022). "The tumor microenvironment might indeed alter the redox status of the three conserved cysteines which are sensitive to oxidation and thus modify the anticancer activities of HMGB1-fl and its derivatives." (PMID 35887213, 2022). "Tumor cells release specific proteins that are characteristic of ICD and feature as danger signals, or DAMPs (danger-associated molecular patterns) including calreticulin (CRT), extracellular adenosine triphosphate (ATP), heat shock protein (HSP), and high mobility group protein B1 (HMGB1)." (PMID 34771120, 2021). "Triptolide significantly suppressed MDA-MB-231 cell viability and clonogenic ability via inhibiting High Mobility Group Box 1 (HMGB1) mRNA expression and its associated factors, e.g., Toll-like receptor 4 (TLR4) and phosphorylated form (p) of NF-κB p65 and inhibited MDA-MB-231 tumor growth." (PMID 34948368, 2021). "In addition, miR-218 functions as a tumor suppressor by targeting the expression of high mobility group box-1 (HMGB1) in NSCLC, suggesting that miR-218 might be a potential therapeutic biomarker for metastatic NSCLC patients." (PMID 33898432, 2021). "We found that HMGB1 deficiency without cisplatin treatment did not affect tumor growth." (PMID 34094941, 2021). "However, the signaling pathways mediated by RAGE are very complex and are characterized by numerous ligands (AGEs, HMGB1, and S100 proteins) and broad receptor expression across many cell types, including endothelial cells, myeloid cells, lymphocytes, and tumor cells." (PMID 33436632, 2021). "After treatment, and in addition to the purely cytotoxic effect, dying tumor cells may emit danger signals, characterized in particular by the extracellular release of HMGB1 or ATP, membrane calreticulin (CRT) exposure, or secretion of type I interferons and chemoattracting chemokines (CXCL10)." (PMID 34885109, 2021). "In addition, HMGB1 has been reported to participate in tumor progression, invasion, and metastasis." (PMID 34966671, 2021). "Consequently, some tumor cells undergo apoptosis or necrosis and release proinflammatory substances, such as adenosine triphosphate (ATP) and high mobility group box 1 (HMGB1), inducing persistent low-grade inflammation and recruiting various immune cells into tumors." (PMID 35070992, 2021). "Furthermore, we suggest that HMGB1-mediated inflammation might contribute to the production of heterogeneous tumor mass involving tumor cells, macrophages and other stromal components." (PMID 34244567, 2021).
tumor (continued). "Thus, CML-HMGB1 exhibited a more significant tumor-promoting effect than HMGB1." (PMID 34068442, 2021). "Therefore, GIHT could be implemented in multimodal therapies since it may take advantage of radio sensitization of tumor cells by inducing the timely release of ATP and HMGB1-DNA complexes during the progress of cell death." (PMID 34485114, 2021). "Moreover, HMGB1 released from dying tumor cells activates DCs through stimulation of TLR2 pathway." (PMID 34084145, 2021). "However, HMGB1 released from dying tumor cells may stimulate bone marrow-derived tumor-infiltrating myeloid dendritic cells through HMGB1/TLR2 signaling." (PMID 33669632, 2021). "In addition to the interaction with tumor cells, HMGB1 could bind to immune cells or other cell types in the tumor microenvironment to elicit a pro-tumoral activity." (PMID 34966671, 2021). "Interestingly, ex vivo modelling of this response suggested that HMGB1 in EVs from irradiated tumour cells could be responsible for this effect on TAM polarisation." (PMID 33467153, 2021). "Moreover, the magnitude of cytosolic translocation of HMGB1 in the tumor cells before neoadjuvant CRT positively correlated with patient survival, implying cytosolic HMGB1 might be a predictive biomarker of treatment outcome." (PMID 33920544, 2021). "HMGB1 release is mandatory for ICD because HMGB1, by interacting with APCs, triggers signalling pathways that allow the antigen to be trafficked towards the antigen-presenting compartment, thereby leading to optimal tumour antigen processing and cross-presentation to T cells." (PMID 34112202, 2021). "Galectin-9 expression in cancer cells lacking functional TLR4 could still be triggered by HMGB1 indirectly via induction of TGF-β expression in TLR4-positive myeloid cells (e.g. tumour-associated macrophages) present in the tumour microenvironment." (PMID 34234778, 2021). "Moreover, it has been reported the paradoxical role of HMGB1 in the tumor microenvironment." (PMID 33807604, 2021). "Nevertheless, there have been reports that HMGB1 may also play a role as a tumor suppressor." (PMID 34721407, 2021). "In addition, higher expression of high mobility group box 1 was found in heterogeneous tumor." (PMID 34244567, 2021). "Unlike with surgical resection, the ablated tumor tissues are not removed, apoptotic or necrotic cells release damage-associated molecular patterns, such as HMGB1, ATP, ROS and calreticulin, which may serve to achieve in situ tumor vaccination." (PMID 33882892, 2021). "DC-derived TIM-3 interacts with HMGB1 to suppress the transport of nucleic acids into endosomal vesicles and reduces the therapeutic efficacy of DNA vaccination and chemotherapy by attenuating the immunogenicity of nucleic acids released from dying tumor cells." (PMID 32660524, 2020). "Thus, we speculate that HMGB1 in tumor-derived EXOs may also affect on the proliferation, differentiation, or migration of MDSCs, although no related reports have been published to date." (PMID 32551121, 2020). "In the present work, we analyzed the expression of HMGB1 redox isoforms in different inflammatory conditions in skeletal muscle, from acute injury to chronic conditions of muscle wasting such as cancer cachexia, in tumor microenvironment, in spleen, and in liver after drug intoxication." (PMID 32670275, 2020). "In addition, it was reported that immunity could influence chemotherapy and radiotherapy by increasing tumor-suppressor factor such as HMGB1 or enhancing the expression of PD-L1 to hamper anti-tumor immunity in different cancers." (PMID 33732636, 2020). "Nevertheless, since this immunosuppressive effect of HMGB1 is observed in established tumors where the tumor environment is likely to contain high levels of ROS, it could be that the inactive oxidized form of HMGB1 is responsible for the observed tolerogenic effects in this scenario." (PMID 33179413, 2020).
tumor (continued). "Although our findings suggest that increased HMGB1 levels within MPEs are capable of promoting T cell recruitment, further studies are necessary to determine the phenotype of recently recruited lymphocytes and if such cells are endowed with tumor-specific reactivity." (PMID 33013860, 2020). "Since HMGB1 can be modified by posttranslational modifications, it is important to assess whether HMGB1 modifications (phosphorylation, nitrosation, glycosylation, etc.)affect the function and survival of tumor MDSCs." (PMID 32551121, 2020). "This suggests that HMGB1 could be a target for selectively enforcing tumor suppression." (PMID 32660524, 2020). "Furthermore, the release of HMGB1 by dying tumor cells was shown to compete with nucleic acid binding to the receptor TIM3 selectively expressed by intratumoral DCs with consequent inhibition of anti-tumor immune responses." (PMID 32486257, 2020). "To examine whether DAMPs are essential for the anti-tumor immune response of Arf1 ablation, we first interfered with the action of ATP and HMGB1 in Lgr5/Arf1/Apc intestinal CSC mice by administering ARL61756 (ARL), oxATP, suramin, and the Toll-like receptor 4 (TLR4) inhibitor." (PMID 31924786, 2020). "Furthermore, inhibition of the HMGB1 or TLR2 signaling pathway was shown to slow tumor metastasis." (PMID 32943604, 2020). "Additionally, HMGB1 may mediate tumor immune escape by promoting the differentiation and proliferation, as well as the immunosuppressive activities, of myeloid-derived suppressor cells (MDSCs)." (PMID 32664328, 2020). "A study found that high migration rate family protein B1 (HMGB1) and other prototype cell damage-related molecular patterns (DAMPs) can increase the clearance rate of organelles in tumor cells that are damaged by antitumor drugs by upregulating autophagy, thereby enhancing tumor drug resistance." (PMID 33055358, 2020). "In addition, increased tumor expression of HMGB1 correlated inversely with tumor differentiation." (PMID 32664328, 2020). "After irradiation, tumour cells can undergo a form of cell death known as immunogenic cell death and express damage-associated molecule patterns (DAMP) or “danger signals”, which includes exposure of calreticulin, the extracellular release of ATP and high mobility group box 1 (HMGB1) and uric acid." (PMID 33008040, 2020). "Besides, another study indicated that HMGB1 synergizes with ATP to induce IL‐1β release by DCs and that antibody specific for HMGB1 abrogated the ability of DCs to produce IL‐1β in contact with dying tumor cells." (PMID 33179413, 2020). "Moreover, the systematic assessment of ICD biomarkers such as the expression of CALR or HMGB1 on tumor biopsies may yield useful information for patient stratification." (PMID 33243969, 2020). "During tumor development and treatment, HMGB1 might play paradoxical roles in promoting both cell survival and death by regulating multiple signaling pathways, including immunity, genomic stability, proliferation, metastasis, metabolism, apoptosis and autophagy." (PMID 31331356, 2019). "We presumed that HMGB1 exposure might dictate the immunogenicity of β-lap-induced tumor cell death." (PMID 31324798, 2019). "We hypothesized that targeting HMGB1 using EP treatment could inhibit DLBCL tumor growth." (PMID 30988279, 2019). "This process, known as immunogenic cell death, is characterized by a variety of tumor cell modifications, i.e., cell surface translocation of calreticulin, extracellular release of adenosine triphosphate and pro-inflammatory factors, such as high mobility group box 1 proteins." (PMID 31649875, 2019). "Interestingly, HMGB1, released by dying cells following exposure to asbestos fibers, has a fundamental role in MM pathogenesis supporting the chronic inflammation that fosters tumor development and immune suppression." (PMID 31355131, 2019). "However, it is unknown whether actively released HMGB1 remains in the tumor microenvironment or enters the blood stream." (PMID 30988279, 2019).